TLR7 (toll like receptor 7)
Diseases named in the same sentence as TLR7 in open-access papers (continued):
Sharing a sentence is not in itself a finding about the gene and the disease.
diffuse large B-cell lymphoma (4 papers, 2015 to 2020). "TLR7 was widely expressed in human follicular lymphoma (FL), diffuse large B cell lymphoma (DBCL) and peripheral T cell lymphoma (PTCL) as well as in other lymphocytic diseases, such as chronic lymphocytic leukaemia (CLL)." (PMID 25887995, 2015). "TLR7/8/9 antagonists are mostly antisense oligonucleotide (ASO) like Bazlitoran (IMO-8400), which was granted orphan drug status for diffuse large B cell lymphoma (DLBCL) and Waldenstrom’s Macroglobulinemia (WM)." (PMID 32708302, 2020).
eosinophilia (4 papers, 2014 to 2024). "CXCL10 upregulation in eosinophilic asthmatic mice has been linked to increased airway hyperreactivity, eosinophilia, and CD8+ T cell recruitment, all of which were evident in TLR7 KO mice at 14 dpi." (PMID 39769461, 2024). "Our data are consistent with this, as IAV-induced lung eosinophilia and the elevated secretion of the Th2 cytokine IL-5 were observed in TLR7 KO." (PMID 39769461, 2024). "Analysis of cell influx into the BAL showed that both TLR agonists significantly reduced lung eosinophilia (TLR7 agonist by 55% and TLR9 agonist by 91%)." (PMID 24618687, 2014). "This suggests that TLR7 plays a role in suppressing eosinophilia during IAV infection." (PMID 39769461, 2024). "The decrease in NK cells observed in the hyperresponsive TLR7 KO mice could therefore contribute to the increased eosinophilia and resultant airway hyperreactivity." (PMID 39769461, 2024). "In contrast, WT mice did not exhibit eosinophilia during the infection, implying that TLR7 loss altered the immune response to enable greater Th2 signaling." (PMID 39769461, 2024). "In our study, the relative proportions of M2 compared to M1 macrophages in the upper airways of WT mice was highest during early infection and, in concordance with eosinophilia and expression of IL-13 in the lung, suggested a Th2 dominant phenotype that was absent in TLR7 KO mice." (PMID 37795093, 2023).
experimental autoimmune encephalomyelitis (4 papers, 2020 to 2022). An autoimmune demyelinating disease of the central nervous system that is produced experimentally in animals by the injection of homogenized brain or spinal cord in Freund's adjuvant. "For TLR7-mediated T cell responses, activation of TLR7 signaling appeared to inhibit the differentiation of Th1 and Th17 cells and thus ameliorated the development and disease severity in the experimental autoimmune encephalomyelitis (EAE) animal model." (PMID 35069523, 2021). "Furthermore, using similar dosage regimens, the TLR7 agonist, Imiquimod, reduced experimental autoimmune encephalomyelitis and increased splenic IFN-β production." (PMID 32327682, 2020).
Histiocytosis (4 papers, 2018 to 2025). An excessive number of histiocytes (tissue macrophages). "Unexpectedly, topical TLR7 treatment caused a severe histiocytosis, hemophagocytosis, and hematologic derangements that resulted in high mortality in both strains of mice." (PMID 31998321, 2019). "Herein, histiocytosis in Slc29a3−/− mice was shown to depend on Toll-like receptor 7 (TLR7), which senses a combination of nucleosides and oligoribonucleotides (ORNs)." (PMID 37462944, 2023). "Spleen pathology and IHC revealed massive expansion of F4/80+ cells in TLR7-treated mice consistent with histiocytosis." (PMID 31998321, 2019). "Spleen histology and flow cytometry revealed massive expansion of histiocytes as well as hemophagocytosis, suggesting that repetitive TLR7 stimulation led to death by histiocytosis/histiocytic sarcoma or from a MAS-like inflammatory syndrome." (PMID 31998321, 2019). "We generated Slc29a3‒/‒Tlr7‒/‒ mice to evaluate the role of TLR7 in histiocytosis." (PMID 37462944, 2023). "However, a specific TLR7 depletion in macrophages would be required to formally prove that TLR7 in macrophages drives histiocytosis in Slc29a3−/− mice." (PMID 37462944, 2023). "Therefore, constitutive TLR7 activation generally drives histiocytosis/monocytosis in mice." (PMID 37462944, 2023). "New evidence indicates that nucleoside accumulation activates TLR7 and TLR8, promoting histiocytosis in Slc29a3−/− mice and in SLC29A3 disorder patients, respectively." (PMID 40037613, 2025). "TLR7 and TLR8 serve as metabolite sensors to activate lysosomal stress responses, which drive histiocytosis unless the stress is relieved." (PMID 37462944, 2023). "Two lines of evidence support the possibility that TLR7 and TLR8 drive histiocytosis in a cell-autonomous manner." (PMID 37462944, 2023). "Mouse TLR8 does not respond to nucleosides and ssRNAs, and negatively regulates TLR7, suggesting that mouse TLR8 might inhibit TLR7-dependent histiocytosis." (PMID 37462944, 2023). "We hypothesized that Guo, dGuo, and Urd accumulate in the compartments where TLR7 and TLR8 are localized and activate TLR7 and TLR8 to drive histiocytosis in SLC29A3 disorders." (PMID 37462944, 2023). "Therefore, macrophage accumulation in Slc29a3−/− mice is completely abolished by the lack of TLR7, suggesting that TLR7-mediated signalling pathways are essential for histiocytosis development in mice." (PMID 40037613, 2025).
immune thrombocytopenia (4 papers, 2011 to 2023). "Using a mouse model of immune thrombocytopenia, we demonstrated an increase in levels of TLR7 in splenic mononuclear cells (SMCs)." (PMID 21818370, 2011). "Similarly, TLR7 was confirmed to promote Th1 polarization and may thus contribute to the pathogenesis of immune thrombocytopenia." (PMID 31930147, 2019).
ischemia (4 papers, 2017 to 2025). A hypoperfusion of the BLOOD through an organ or tissue caused by a PATHOLOGIC CONSTRICTION or obstruction of its BLOOD VESSELS, or an absence of BLOOD CIRCULATION. "Multiple microglia-related genes such as Cxcl10, Tlr7, Cd86, Tnfrsf1a, Nfkbia, Tgfb1, Ccl2 and Il-6, were upregulated with prolonged ischemia." (PMID 35154109, 2022). "This is consistent with recent data suggesting that miRNA (18–23 bases) released into the circulation and extracellular space during ischemia may instead trigger cytokine production via endosomal TLR7/MyD88 signaling." (PMID 30367171, 2018).
Lewis lung carcinoma (4 papers, 2016 to 2021). "In primary myoblasts from toll-like receptor 7 (TLR7)−/− mice incubated with conditioned medium from Lewis lung carcinoma cells, the cell death was significantly reduced when compared with myoblasts from TLR7+/+ incubated with the same conditioned medium." (PMID 32325796, 2020).
lung adenocarcinoma (4 papers, 2020 to 2025). A carcinoma that arises from the lung and is characterized by the presence of malignant glandular epithelial cells. "Based on the cBioPortal database, we obtained TLR7 gene alterations in pan-cancer patients with higher mutations in endometrial cancer of the uterus, skin and skin melanoma, uterine carcinosarcoma, lung squamous cell carcinoma, and lung adenocarcinoma." (PMID 37362864, 2023). "The objective of this study is to elucidate the relationship between toll-like receptor 7 and the clinical characteristics of patients with lung adenocarcinoma." (PMID 39857735, 2025). "Subsequently, we validated the expression of TLR7 in lung adenocarcinoma and its effect on survival in the GEO, which further refined our findings." (PMID 39857735, 2025). "TLR7 expression in lung adenocarcinomas correlates with immune infiltration levels, including B cells, CD4+ T cells, CD8+ T cells, dendritic cells, and macrophages." (PMID 39857735, 2025). "In conclusion, the discovery of TLR7 offers new hope for biomarkers and potential therapeutic targets for lung adenocarcinoma." (PMID 39857735, 2025). "The survival analysis revealed a link between lung adenocarcinoma survival and B cells, DC cells, and TLR7 expression." (PMID 39857735, 2025). "Consistently, the administration of the TLR7 agonist loxoribine to mice grafted with lung adenocarcinoma cells increased chemotherapeutic resistance." (PMID 33578955, 2021). "In particular, the authors demonstrate that the TLR7 agonist had a superior tumor inhibitory effect in a metastatic model of lung adenocarcinoma, relative to anti-PD1 therapy or platinum-based chemotherapy." (PMID 33578955, 2021). "In conclusion, TLR7 is a reliable clinical indicator for predicting patient prognosis, immunotherapy response, and potential drug targets, thus providing new perspectives on therapeutic approaches for lung adenocarcinoma." (PMID 39857735, 2025). "TILs (Tumor Infiltrating Lymphocytes) in TCGA lung adenocarcinoma samples were determined using the TIMER algorithm, and we analyzed how changes in TIL components correlate with TLR7 expression." (PMID 39857735, 2025). "In addition, we also verified at the cellular and tissue levels by qPCR, WB, and IHC that TLR7 expression was higher in normal bronchial epithelial cells and adjacent normal tissues than in LUAD cell lines and lung adenocarcinoma tissues." (PMID 39857735, 2025).
lung fibrosis (4 papers, 2017 to 2026). "In a murine model of SSc, deletion of TLR7 attenuated skin and lung fibrosis and was associated with reduced infiltration of pro-inflammatory and profibrotic immune cells and cytokines in the skin." (PMID 41614927, 2026). "In conclusion, the attenuation of skin and lung fibrosis caused by the TLR7 deletion was achieved through the polarized state of M2 in the spleen, followed by the migration of M2 macrophages to the target organs, ultimately inhibiting chronic inflammation and fibrosis." (PMID 38892317, 2024). "The histological analysis revealed that TLR7-KO mice treated with bleomycin had less lung fibrosis than BLM-treated WT mice, whereas TLR9-KO mice treated with bleomycin had more lung fibrosis than BLM-treated WT mice." (PMID 38892317, 2024). "Although the ability of a folate‐targeted TLR7 agonist to treat fibrosis was only examined in a murine model of lung fibrosis, we envision that the same strategy might also prove beneficial in treatment of fibrotic diseases of the liver, skin, heart, and the kidneys." (PMID 32597014, 2020). "In a mouse model of SSc disease, the deletion of TLR7 attenuated skin and lung fibrosis, while the deletion of TLR9 exacerbated skin and lung fibrosis." (PMID 38892317, 2024). "Studies in other injury models and investigations in patients with idiopathic pulmonary fibrosis (IPF) suggest a contribution of further TLR such as TLR3, TLR7 or TLR9 in the pathogenesis of pulmonary fibrosis." (PMID 28836991, 2017). "A folate‐targeted TLR7 agonist (FA‐TLR7‐54) is shown to alleviate pulmonary fibrosis with no detectable toxicity." (PMID 32597014, 2020).
myocardial infarction (4 papers, 2018 to 2025). Gross necrosis of the myocardium, as a result of interruption of the blood supply to the area, as in coronary thrombosis. "Some of the most commonly used mouse strains to study thrombosis and myocardial infarction in SLE are mice with mutations in Fas or FasL, or with overexpression of Toll-like receptor 7 (TLR7)." (PMID 35419427, 2022). "After myocardial infarction, gene expression levels of the intracellular localized Tlr7, Tlr8, and Tlr9 were significantly increased when compared to their healthy controls." (PMID 29538462, 2018). "In this study, we observed highly increased gene expression levels of Tlr1, Tlr2, Tlr6, Tlr7, Tlr8, Tlr9 as well as Irf7 in the scar tissue after myocardial infarction, indicating their relevance to a proper cardiac wound healing." (PMID 29538462, 2018). "Activation of TLR7 has been shown to be essential for miR146a-5p-induced myocardial inflammation and cardiomyocyte dysfunction in mice, and both human and mouse cardiac tissue exhibit upregulated TLR7 gene expression following myocardial infarction (MI)." (PMID 39828779, 2025). "Interestingly, post myocardial infarction TLR and IRF gene expression was almost exclusively increased in the infarct zone after myocardial ischemia (Tlr2, Tlr3, Tlr6, Tlr7, Tlr9, Irf3, Irf7)." (PMID 29538462, 2018).
osteoarthritis (4 papers, 2022 to 2025). A noninflammatory degenerative joint disease occurring chiefly in older persons, characterized by degeneration of the articular cartilage, hypertrophy of bone at the margins and changes in the synovial membrane. "Intra-articular injection of a TLR7 antagonist also attenuates mechanical allodynia in a rat osteoarthritis model induced by anterior cruciate ligament transection." (PMID 41511304, 2025). "In addition, in the surgical osteoarthritis (OA) rat model, the upregulated TLR7 in synovial tissue mediated knee OA pain, as single intra-articular injection of TLR7–9 antagonist exerted long-term analgesia." (PMID 35141864, 2022). "The expression levels of TCA1, TLR7, MMP9, CXCL10, CXCL13, HLA-DRA, and ADIPOQSPP1 were significantly higher in the IL-1β-induced group than in the osteoarthritis group in an in vitro qPCR experiment." (PMID 35734177, 2022).
pertussis (4 papers, 2020 to 2024). A contagious bacterial respiratory infection caused by Bordetella pertussis. "One unavoidable shortcoming worth highlighting of studies such as ours, that focus on TLR7/8 agonist adjuvant development, is the reduced applicability of pertussis challenge model in mice." (PMID 36258023, 2022). "TLR7/8A:alum represents a promising adjuvant combination that may enable an improved pertussis vaccine to optimally protect the very young." (PMID 36258023, 2022).
Pneumovirus Infections (4 papers, 2016 to 2019). Infections with viruses of the genus PNEUMOVIRUS, family PARAMYXOVIRIDAE. "Also, TLR7 pathway in pDCs were associated with host protection against rodent-specific pneumovirus infection." (PMID 31398816, 2019). "Thus, the coordinated antiviral host response to pneumovirus infection requires both an RLR/IPS-1 signal to induce the recruitment of pDCs, as well as TLR7-mediated activation of the recruited pDC18, explaining the non-redundant role of both PRRs." (PMID 28539639, 2017). "Nevertheless our findings that IPS-1 signalling is required to increase pDCs in the lung provides a possible mechanism to explain the non-redundant role of both the RLR/IPS-1 signalling and TLR7/MyD88 signalling in the generation of optimal host defence against pneumovirus infection." (PMID 28539639, 2017).
preeclampsia (4 papers, 2012 to 2022). Preeclampsia is a hypertensive disorder of pregnancy that is characterized by new-onset hypertension with proteinuria presenting after 20 weeks of gestation, and depending on mild or severe forms may initially present with severe headache, visual disturbances, and hyperreflexia. "In the study, we devote to investigate the associations of FOXO3 and TLR7 genetic polymorphisms with preeclampsia in a Chinese population." (PMID 33317466, 2020). "Another study utilizing another group of multiple preeclampsia gene sets showed mainly immune-related genes (bone morphogenetic protein 5 (BMP5), cell surface glycoprotein (CD) 200R1 (CD200R1) and 28 (CD28), and TLR7) that are differentially expressed in preeclampsia." (PMID 35269385, 2022). "In preeclampsia, placental expression of TLR3, TLR7, and TLR8 are upregulated." (PMID 32260307, 2020).
rosacea (4 papers, 2021 to 2025). A chronic erythematous skin disorder that affects the face. "This phenomenon illustrated that keratinocytes can sense pathogenic factors through TLR7 independently of other immune cells in the pathogenesis of rosacea, and act as immune targets and initiators to start inflammatory responses." (PMID 37780385, 2023). "To summarize, excess stimulation of TLR7 regulating rosacea-associated cytokines and chemokines to recruit T cells is dependent on NFκB signaling." (PMID 37780385, 2023). "Collectively, these results proved that TLR7 deficiency could prevent the development of rosacea, which may put forward a novel treatment strategy." (PMID 37780385, 2023). "However, the underlying mechanism of how TLR7 regulates NF κB in rosacea calls for intensive research." (PMID 37780385, 2023). "The study demonstrated that TLR7 was overexpressed in rosacea lesions, activating the NF-κB/mTORC1 pathway and promoting cytokine and chemokine production in keratinocytes." (PMID 41373451, 2025). "Here, via RNA-sequencing analysis, we found that the TLR signaling pathway is the top-ranked signaling pathway enriched in rosacea skin lesions, in which TLR7 is highlighted and positively correlated with the inflammation severity of disease." (PMID 37780385, 2023). "Mice results showed that 12 hours after the last time of LL37 injection, LL37-induced mice presented typical rosacea-like skin inflammation in Scr siRNA groups while Tlr7 siRNA groups with LL37 exhibited alleviated rosacea characteristics." (PMID 37780385, 2023). "Taken together, our results emphasize the key function of the TLR7 pathway in the pathogenesis of rosacea and open up new possibilities for rosacea treatment." (PMID 37780385, 2023). "Collectively, our observations revealed that TLR7 is essential in rosacea development and has the proficiency to be a therapeutic target of rosacea." (PMID 37780385, 2023). "Our experiment uncovered mTORC1 signaling stimulated by TLR7 results in cytokines/chemokines’ production and T cells’ enrichment in rosacea." (PMID 37780385, 2023). "Altogether, these findings illustrated the indispensable role of epidermal TLR7 in rosacea inflammatory loops." (PMID 37780385, 2023). "In human keratinocytes, hyperactivated TLR7 stimulates NFκB/mTORC1 and rosacea-characteristic cytokines and chemokines, eventually leading to skin inflammation of rosacea." (PMID 37780385, 2023). "In LL37-induced rosacea-like mouse models, silencing TLR7 prevented the development of rosacea-like skin inflammation." (PMID 37780385, 2023). "Our report reveals the crucial role of TLR7 in rosacea pathogenesis and indicatesa promising candidate for rosacea treatments." (PMID 37780385, 2023). "Considering that TLR7 is mainly upregulated in epidermal keratinocytes in rosacea, we transfected keratinocytes with ectopic expression vector to overexpress TLR7 to explore the underlying molecular mechanism regulating rosacea formation." (PMID 37780385, 2023). "Meanwhile, RT-qPCR reflected that rosacea-related pro-inflammatory cytokines increased by LL37 were improved when epidermal TLR7 was silenced, for instance, Tnf-α, Il6 and Il-1β." (PMID 37780385, 2023). "Eventually, the TLR7/NFκB/mTORC1 axis promoted the production of rosacea-correlative cytokines and chemokines, leading to the migration of CD4+ T cells, which is involved in the process of rosacea development." (PMID 37780385, 2023). "In our study, we revealed TLR7 was overexpressed in rosacea, and specific knockdown of TLR7 in skin will prevent the development of rosacea in a mouse model." (PMID 37780385, 2023). "Taken together, this evidence explained that stimulated TLR7 in keratinocytes activates the NFκB signal pathway in rosacea." (PMID 37780385, 2023). "TLR7 plays a key role in the pathogenesis of rosacea by activating the NFκB-mTORC1 axis." (PMID 38341589, 2024).